CRP (C-reactive protein)
Diseases named in the same sentence as CRP in open-access papers (continued):
Sharing a sentence is not in itself a finding about the gene and the disease.
Neonatal sepsis (continued). "The keywords used in the search were C-reactive protein, procalcitonin, and neonatal sepsis." (PMID 40970024, 2025). "For example, novel nanotechnology-based biosensors have achieved rapid detection of pathogens in serum samples within seconds, and POCT systems for biomarkers like C-reactive protein, procalcitonin, and interleukin-6 are increasingly used in neonatal sepsis management." (PMID 40830514, 2025). "A literature search was conducted, from May 1 to May 19, 2025, to identify relevant articles comparing the accuracy of C-reactive protein and procalcitonin in diagnosing neonatal sepsis." (PMID 40970024, 2025). "On the contrary, neonatal CRP is widely used in the diagnosis of neonatal sepsis." (PMID 40310124, 2025). "Abnormal clinical and laboratory results, such as hypothermia, tachypnea, leukocytosis, an elevated level of C-reactive protein, an Apgar score of 6 at the fifth minute of life, and a birth weight of 2.3 kg, were used to diagnose neonatal sepsis, perinatal asphyxia, and LBW." (PMID 41311440, 2025). "While some studies suggest that procalcitonin may have higher accuracy than CRP in predicting neonatal sepsis, others indicate that the comparison between procalcitonin and CRP remains controversial." (PMID 40809608, 2025). "The platelet-to-C-reactive protein ratio (PCR), an objective and convenient biomarker integrating information on disseminated intravascular coagulation and systemic inflammation, has demonstrated predictive value in neonatal sepsis and other conditions." (PMID 41550605, 2025). "There is a high correlation between CRP and blood culture in patients with neonatal sepsis which may give access to remodeling the prioritization of the management options in the clinical setting." (PMID 38654771, 2024). "Other studies demonstrated the clinical value of CRP as a predictor of neonatal sepsis." (PMID 38790588, 2024). "Another thoroughly investigated laboratory marker used to diagnose neonatal sepsis is CRP." (PMID 39457166, 2024). "Neonatal sepsis may be more sensitive to the combination of IL-8 and CRP, guiding clinicians in the rational use of antibiotics." (PMID 38848433, 2024). "Initially, neonatal sepsis investigations showed unremarkable hemoglobin (16.7 g/dl) and platelet levels (183,000/L), but his C-reactive protein (CRP) (22.3 mg/L), procalcitonin (34.7 μg/L), and white blood cell levels (total white blood cell count 21,670/mm3) were increased." (PMID 39867692, 2024). "CRP is widely recognized as a biomarker in the diagnosis of neonatal sepsis." (PMID 39498415, 2024). "The CRP to platelet ratio (CPR) is currently being evaluated for its role in neonatal sepsis." (PMID 39006693, 2024). "Analysis of the CRP-to-platelet ratio can aid in the diagnosis of neonatal sepsis." (PMID 39006693, 2024). "Hence, in our study, out of all the researched biomarkers, procalcitonin (AUC—0.78) and CRP measured on the first day (AUC—0.76) had the best predictive performance for early-onset neonatal sepsis." (PMID 38255436, 2024). "Although this study may have some limitations, for the diagnosis of neonatal sepsis, the sensitivity of biomarkers is more important than the specificity, so PTX-3 seems to be superior to CRP as a diagnostic biomarker for neonatal sepsis." (PMID 39021820, 2024). "Studies suggest that assessing presepsin and CRP, PCT or IL-6 together may improve diagnostic procedures and patient outcomes particularly in neonatal sepsis." (PMID 38921759, 2024). "The study proved that there is a high correlation between CRP and blood culture in patients with neonatal sepsis which may give access to remodeling the prioritization of the management options in the clinical setting." (PMID 38654771, 2024). "A higher CRP-to-platelet ratio in culture-positive neonates than in culture-negative neonates supports the role of the CRP-to-platelet ratio in the diagnosis and management of neonatal sepsis." (PMID 39006693, 2024).
Neonatal sepsis (continued). "Moreover, our results showed that a combination of biomarkers (WBC, CRP, and fibrinogen), evaluated on the first and third day of life, had superior accuracy in detecting early onset neonatal sepsis (AUC: 0.83, AND 0.90, respectively)." (PMID 38255436, 2024). "Another study suggested a relationship between neonatal sepsis and maternal third-trimester CRP, and indicated the possibility that this effect might be dependent on the gestational age." (PMID 39201697, 2024). "A Random Effects GLS regression was used to measure the association between predictor variables, such as serum and hematological biomarkers levels (WBC, CRP, and fibrinogen) measured on three different occasions, and an outcome variable, proven early-onset neonatal sepsis." (PMID 38255436, 2024). "When compared with CRP, blood culture, and serum procalcitonin levels, the ROC curves generated sensitivity and specificity levels with cut-off values of serum calprotectin to detect neonatal sepsis." (PMID 37600908, 2023). "In neonatal sepsis, its concentrations rise after 4 h from the proinflammatory effect of bacterial endotoxins, and reach their peak after 6–8 h, thus rising earlier than CRP." (PMID 37755410, 2023). "However, the combination of PCT and CRP or presepsin alone improved the accuracy of diagnosis of neonatal sepsis, as shown in a meta-analysis of 28 studies enrolling 2661 neonatal patients." (PMID 36830264, 2023). "However, the strongest predictors across most studies focusing on neonatal sepsis were gestational age, C-reactive protein levels, white cell count, platelet count, heart rate, and respiration." (PMID 37386442, 2023). "If CRP remains normal persistently then bacterial neonatal sepsis is unlikely." (PMID 35633256, 2022). "CRP is the most common laboratory tests in the diagnosis of neonatal sepsis, which will take around 10 to 12 h for level to increase, so making it low sensitive for early diagnosis of neonatal sepsis." (PMID 35664882, 2022). "Gestational age, CRP, considerable skin discoloration, liver enlargement, neutrophil left shift, and EXTEM A10, were identified as the strongest predictors and included in the Neonatal Sepsis Diagnostic (NeoSeD) model." (PMID 36275071, 2022). "CRP itself cannot diagnose neonatal sepsis because of low sensitivity and specificity." (PMID 35633256, 2022). "In addition, we noted an increase of mortality and increased CRP values in patients with neonatal sepsis." (PMID 36553264, 2022). "The diagnostic value of LL37, CRP, and WBC for early onset neonatal sepsis." (PMID 35664882, 2022). "Thus, isolated CRP values don’t seem convincing as the point of care test for neonatal sepsis in surgical neonates." (PMID 36158418, 2022). "By use of ROC analysis we demonstrated that CRP could play a role in the early diagnosis of neonatal sepsis if cut-off values were lowered." (PMID 35345614, 2022). "This manifestation and high serum CRP levels in three infants are common in neonatal sepsis." (PMID 34188437, 2021). "Similarly, the combination of CD64 and CRP was found to be more sensitive for neonatal sepsis than either measure alone." (PMID 34720754, 2021). "Alarmingly, 21% of the neonatal sepsis patients enrolled in this study died during the treatment, which demand better treatment compliance through regular monitoring of CRP levels, review of culture and frequent consideration of other physiological parameters to timely start interventions." (PMID 33439876, 2021). "Additionally, even though CRP is commonly used as a marker for neonatal sepsis, recent clinical studies claimed the need of other salivary markers for diagnosis due to unreliable screening validity of salivary CRP." (PMID 33673378, 2021). "CRP is proposed to serve as a screening biomarker for neonatal sepsis." (PMID 33833617, 2021). "CRP is most commonly used to diagnose neonatal sepsis and decide antibiotic treatment suspension." (PMID 34572631, 2021).
Neonatal sepsis (continued). "CRP is produced by the liver and is increased in response to early-onset neonatal sepsis." (PMID 34900858, 2021). "CRP is the most commonly available test in hospitals for neonatal sepsis." (PMID 33407770, 2021). "The clinical identification and diagnosis of neonatal sepsis is confirmed by blood culture, and the assessment of acute phase reactants includes C-reactive protein (CRP), procalcitonin, presepsin, and inflammatory mediators such as interleukin-6 (IL-6) and tumor necrosis factor-alpha (TNFα)." (PMID 34900858, 2021). "We believe that the CRP/MPV ratio may offer an advantage in the early diagnosis of neonatal sepsis which could be superior to either CRP or MPV when evaluated alone." (PMID 34676267, 2021). "IL-6 and CRP are being used most commonly for the diagnosis of neonatal sepsis." (PMID 33233806, 2020). "Therefore, this study aimed to assess the usefulness of CRP as an inflammatory biomarker in the prediction of neonatal sepsis in Butembo, the Democratic Republic of the Congo." (PMID 32238170, 2020). "Therefore, this study aimed to assess the usefulness of C-reactive protein (CRP) as an inflammatory biomarker in the prediction of the neonatal sepsis diagnosis in Butembo, the Democratic Republic of the Congo, in sub-Saharan Africa." (PMID 32238170, 2020). "Other blood investigations that may be done in diagnosing neonatal sepsis include full blood count and acute phase reactants, such as the C-reactive protein (CRP)." (PMID 32238170, 2020). "The diagnostic performance of these combinations is higher than the use of IL-6 or CRP alone as these combinations showed markedly increased sensitivity and NPV with a slightly decreased specificity and PPV compared with the use of IL-6 or CRP alone for the diagnosis of neonatal sepsis." (PMID 33233806, 2020). "CRP showed its usefulness in the diagnosis of neonatal sepsis." (PMID 32238170, 2020). "However some studies have found low sensitivity and specificity of CRP in diagnosing the neonatal sepsis." (PMID 29492073, 2017). "Serum CRP level is a reliable test in establishing the diagnosis of neonatal sepsis." (PMID 29492073, 2017). "Among the various tests CRP role in neonatal sepsis has been vastly studied." (PMID 26150837, 2015). "So we cannot comment on the rising titer of the CRP in neonatal sepsis." (PMID 26150837, 2015). "The role of CRP in diagnosing neonatal sepsis is well studied." (PMID 25909192, 2015). "Thus, a prospective study is warranted to scientifically delineate the sensitivity and specificity of CRP as a predictive marker of neonatal sepsis." (PMID 26259626, 2015). "Similarly, CRP is ordered routinely on all neonates with suspected neonatal sepsis in the neonatal intensive care unit." (PMID 22943554, 2012). "CRP may also be invaluable in the management of neonatal sepsis in resource poor centres where facilities for blood culture may not be readily available." (PMID 22958461, 2012). "The C-reactive protein may therefore, help in the early detection of neonatal sepsis while awaiting blood culture results." (PMID 22958461, 2012). "We conclude that procalcitonin is a better marker than CRP in the diagnosis of neonatal sepsis." (PMID 23493845, 2012). "The most widely used acute phase reactant for the diagnosis of neonatal sepsis is CRP." (PMID 21765851, 2011). "Our systematic review found that although CRP is widely utilized due to its low cost and simplicity, its limited early sensitivity and susceptibility to non-infectious factors reduce its utility in diagnosing neonatal sepsis." (PMID 40970024, 2025). "Additionally, we also evaluated the ability of PCT, ALB and CRP to predict neonatal sepsis." (PMID 36908271, 2023). "Additionally, it has superior sensitivity to CRP in neonatal sepsis diagnostics 45-48." (PMID 35582414, 2022).
Neonatal sepsis (continued). "Owing to the physiological background of the major conventional indicators for neonatal sepsis in premature infants, the cut-off value of CRP, PCT, and blood routine required for EOS diagnosis could be affected by the postnatal time (such as 6, 24, and 72 hours)." (PMID 36086701, 2022). "Furthermore, a tiny change of blood CRP concentration may portend chronic diseases, such as cardiovascular diseases, peripheral vascular diseases, and neonatal sepsis; therefore, high-sensitivity CRP (hs-CRP) detection at a level of 1 ng/mL is demanded." (PMID 36354486, 2022). "Hence, for the early diagnosis IL-6 (from cord blood or peripheral neonatal blood) and later repetitive measurements of CRP seem to be helpful in the diagnosis of neonatal sepsis considering the clinical aspect of the neonate, its gestational age, maternal risk factors, and the time of sampling." (PMID 35345614, 2022). "Also, salivary CRP was investigated as a noninvasive marker for the diagnosis of neonatal sepsis." (PMID 34676267, 2021). "Thus, in contrast to CRP levels and lymphocyte counts, examination of the cytokine profile can provide valuable information when determining the most effective therapy for treating neonatal sepsis." (PMID 28367457, 2017). "Both C-reactive protein (CRP) and procalcitonin (PCT) are traditionally used serum markers for the diagnosis of neonatal sepsis." (PMID 40506913, 2025). "Melatonin improved CRP, WBC, and clinical condition within 72 h; effective adjunct in neonatal sepsis." (PMID 41293242, 2025). "This systematic review aims to compare the diagnostic accuracy and clinical utility of C-reactive protein (CRP) and procalcitonin (PCT) in the early diagnosis of neonatal sepsis." (PMID 40970024, 2025). "The AUC for diagnosing neonatal sepsis and neonatal infections with HBP are 0.885 and 0.904, respectively, both higher than those for PCT and high-sensitivity C-reactive protein (hs-CRP)." (PMID 39193501, 2024). "The AUC for HBP in diagnosing neonatal sepsis was 0.885, which was higher than that for PCT and hs-CRP." (PMID 39193501, 2024). "While CRP is commonly used as a biomarker for acute inflammation, it is not as sensitive as neutrophil CD64 expression when diagnosing neonatal sepsis." (PMID 38596677, 2024). "C-reactive protein (CRP) and procalcitonin (PCT) are the most widely used biomarkers of neonatal sepsis, but their accuracy is still disputed." (PMID 39330888, 2024). "Although C-reactive protein (CRP) and procalcitonin (PCT) are the most widely used biomarkers of neonatal sepsis, their accuracy is still controversial." (PMID 38535886, 2024). "In this study, we aimed to assess the correlation between positive cultures, high C-reactive protein (CRP) levels, and the diagnosis of neonatal sepsis." (PMID 38654771, 2024). "PSP has been also investigated in neonatal sepsis showing a performance comparable or superior to other biomarkers (PCT, CRP)." (PMID 37805604, 2023). "While limited studies have compared the CRP and PCT in neonatal sepsis, a study has reported improved diagnosis of neonatal sepsis with the combination of PCT and CRP." (PMID 36158418, 2022). "Various laboratory biomarkers such as interleukins (ILs), tumor necrosis factor (TNF), C-reactive protein (CRP), procalcitonin (PCT), and immunoglobulins have been considered for the diagnosis of neonatal sepsis." (PMID 37551395, 2022). "Regarding early onset neonatal sepsis (3 EONS vs. 10 controls), cfDNA, DNase I, nucleosome, and CRP were elevated significantly." (PMID 35053308, 2022). "Measurement of CRP and Total Leukocyte Count (WBC) after 48 hours of clinicalsymptoms were considered promptly for diagnose neonatal sepsis." (PMID 37654832, 2022). "In this study, we evaluated the diagnostic value of salivary IL-10 as a noninvasive marker as well as serum IL-10, CRP, MPV, and CRP/MPV ratio in early diagnosis of late-onset neonatal sepsis in full-term neonates." (PMID 34676267, 2021).
Neonatal sepsis (continued). "In the ROC analysis, the area under the curve (AUC) for CRP and NLR for the diagnosis of neonatal sepsis was 0.918 (p=<0.001) and 0.623 (p=0.042), respectively." (PMID 33643735, 2021). "CRP and band forms were more helpful than C-reactive protein and immature to total neutrophil ratio and micro-ESR in the screening of early neonatal sepsis." (PMID 34899922, 2021). "We aimed to investigate the diagnostic role of salivary and serum interleukin 10 (IL-10), C-reactive protein (CRP), mean platelet volume (MPV), and CRP/MPV ratio in the diagnosis of late-onset neonatal sepsis in full-term neonates." (PMID 34676267, 2021). "Recent studies indicate that P-SEP can be used to monitor clinical response to therapeutic interventions prior to obtaining culture results, confirming it as a more reliable biomarker than CRP and PCT in neonatal sepsis." (PMID 34830040, 2021). "Although CRP and PCT are the most widely used biomarkers of neonatal sepsis, their accuracy is still controversial." (PMID 34830040, 2021). "In the ROC analysis, the AUC for CRP and NLR for the diagnosis of neonatal sepsis were 0.918 (p=<0.001) and 0.623 (p=0.042), respectively." (PMID 33643735, 2021). "Inflammatory protein markers such as those regulated by IL-6, like C-reactive protein (CRP), are important clinical analytes for early onset neonatal sepsis." (PMID 34597920, 2021). "C-reactive protein (CRP) is one of the most widely used and studied acute-phase reactants for neonatal sepsis as it is fast, cost-effective and simple." (PMID 33218324, 2020). "Multicenter prospective studies are required to clarify the utility of LRG in comparison with CRP, PCT, and IL-6 in detecting fetal infection as well as neonatal sepsis." (PMID 33211747, 2020). "This study was done to investigate the role of CRP, PCT, and IL-6 in promoting the early diagnosis of neonatal sepsis in an attempt to decrease morbidity and mortality." (PMID 33061986, 2020). "The combination of CRP and PCT resulted in higher sensitivity and AUC and lower NLR, which helped in confirming and ruling out neonatal sepsis." (PMID 30463590, 2018). "Our aim was to compare the diagnostic accuracy of procalcitonin (PCT), C-reactive protein (CRP), procalcitonin combined with C-reactive protein (PCT + CRP) and presepsin in the diagnosis of neonatal sepsis." (PMID 30463590, 2018). "C-reactive protein (CRP) and procalcitonin (PCT) have some limitations in the diagnosis of preterm neonatal sepsis." (PMID 30068303, 2018). "Serum C-reactive protein (CRP) and procalcitonin (PCT) are two of the most thoroughly investigated laboratory markers used to diagnose neonatal sepsis." (PMID 30068303, 2018). "Scattergrams evaluating the positive likelihood ratios in the diagnosis of neonatal sepsis for CRP (A), PCT (B), PCT plus CRP (C), and presepsin (D)." (PMID 30463590, 2018). "There are few studies which evaluated the significance of CRP and WBC count in the diagnosis of neonatal sepsis in developing countries, and as to author’s knowledge, there is no study from Ethiopia." (PMID 30069260, 2018). "Nowadays various biochemical markers, such as C-Reactive Protein (CRP), Procalcitonin and tumor necrosis factor alpha, have been proposed as a potential marker for screening neonatal sepsis." (PMID 30069260, 2018). "A variety of biological indicators, such as serum C-reactive protein (CRP), and numeration of leukocyte (WBC) have been used in the laboratory to diagnose neonatal sepsis." (PMID 28758124, 2017). "In final The combination of IL-6, hs-CRP, and PCT seems to be predictive in diagnosis of early onset neonatal sepsis." (PMID 22708043, 2012). "Improvements in CRP use: Suggestions to improve CRP use in the detection of neonatal sepsis include recognizing non-infectious conditions that affect CRP levels, and being aware of these conditions during the interpretation of values." (PMID 40970024, 2025).